PRKDC (protein kinase, DNA-activated, catalytic subunit)
Diseases named in the same sentence as PRKDC in open-access papers (continued):
Sharing a sentence is not in itself a finding about the gene and the disease.
Autoimmunity (10 papers, 2012 to 2026). The occurrence of an immune reaction against the organism's own cells or tissues. "Patients who were diagnosed with granuloma and autoimmunity with PRKDC mutations exhibited an incapability in DSB repair, V(D)J recombination, and a strong interferon signature." (PMID 38898995, 2024). "Missense mutations of PRKDC, which encodes the catalytic subunit in DNA-PK, were also found in patients with the organ-specific autoimmunity phenotype." (PMID 34970273, 2021). "Our study also provides a rational explanation for the autoimmunity phenotype observed in patients with PRKDC mutations, suggesting that the cGAS-mediated immune signaling is a potential target for therapeutic interventions." (PMID 33273464, 2020). "This study provides a rational explanation for the autoimmunity of patients with missense mutations of PRKDC, and suggests that cGAS-mediated immune signaling is a potential target for therapeutic interventions." (PMID 33273464, 2020).
bladder cancer (10 papers, 2013 to 2025). "Moreover, another article has suggested that circ-PRKDC deficiency leads to a reduction in β-catenin expression in bladder cancer cells, while miR-375 deletion rescued the effects." (PMID 35127344, 2022). "In our study, the prevalence of PRKDC mutations in two large cohorts was identified in multiple solid tumor types, including common neoplasms such as gastrointestinal cancers, NSCLC, and bladder carcinoma." (PMID 32502294, 2020). "Thus, the individual molecular background of bladder cancer patients, including biallelic ATR or PRKDC deficiencies, should be considered in future studies, which may finally allow treatment of patients with a single drug but with comparable efficacy of tumor cell lethality." (PMID 35740300, 2022).
endometrial cancer (9 papers, 2014 to 2023). Primary or metastatic malignant neoplasm involving the endometrium (mucous membrane that lines the endometrial cavity). "The XRCC7 or PRKDC gene (which encodes DNA-PK) has also been reported to present a higher mutation rate in certain types of cancers, such as colorectal, gastric, and endometrial cancers." (PMID 37373360, 2023). "CPQ-PRKDC occurs at a low frequency in endometrial cancer (2.5%, 3/122), and is formed by the rearrangement of exons 1–2 of CPQ and exons 80–87 of PRKDC on chromosome 8." (PMID 34381020, 2021). "We used microarray data for mRNA expression, downloaded from the CCLE data repository, to examine the expression of PRKDC mRNA in endometrial cancer cell lines." (PMID 26689674, 2015). "Of 240 TCGA endometrial cancer samples, three samples (1.3%) showed PRKDC amplifications with concurrent overexpression." (PMID 26689674, 2015). "In the Lander's endometrial carcinoma cohort, the TMB of the PRKDC mut+ samples is significantly higher than in the PRKDC mut− samples in both MSI‐H and MSI‐L/MSS subtypes (median nonsynonymous mutations 558 vs. 220, P < 0.001 in MSI‐H subgroup, 5764 vs. 31, P < 0.0001 in MSS/MSI‐L subgroup)." (PMID 32502294, 2020). "The expression of the total PRKDC transcript in the CPQ-PRKDC fusion-positive cell line was relatively higher than that in the other endometrial cancer cell lines that did not have the CPQ-PRKDC fusion." (PMID 26689674, 2015).
lung adenocarcinoma (9 papers, 2017 to 2023). A carcinoma that arises from the lung and is characterized by the presence of malignant glandular epithelial cells. "Based on these data, we deleted either ATM or the related protein kinase DNA-PKcs/PRKDC from A549 lung adenocarcinoma cell lines using CRISPR/Cas9, and used these cells to examine the mechanism of action of olaparib." (PMID 31481733, 2019). "Analysis of the RNA-seq data from The Cancer Genome Atlas data showed that key NHEJ genes such as PRKDC and XRCC6 are expressed at higher levels in lung SqCC compared to lung adenocarcinomas and normal lung tissue." (PMID 28125611, 2017).
neuroblastoma (9 papers, 2009 to 2026). Neuroblastoma (NB) is the most common solid, extracranial childhood tumor. "Together with the observation that neuroblastoma patients have increased levels of the gene encoding for DNA-PKcs (i.e. PRKDC), these results make DNA-PKcs a promising target for neuroblastoma radiosensitization." (PMID 26716839, 2015). "Elevated PRKDC mRNA levels in neuroblastoma were associated with poor clinical characteristics and a significant reduction in overall survival." (PMID 26716839, 2015). "The results above highlighted PRKDC inhibition as a particularly high-potential combination with doxorubicin in neuroblastoma." (PMID 37957169, 2023). "PRKDC mRNA expression levels were enhanced in patients with neuroblastoma and correlated with a more advanced tumour stage and poor prognosis." (PMID 37240360, 2023). "Future studies need to focus on the PRKDC mRNA cutoff values above which NU7026 radiosensitizes neuroblastoma cells and on the correlation between PRKDC mRNA levels and DNA-PKcs protein levels in neuroblastoma." (PMID 26716839, 2015). "Optimal doses for combination treatment with NU7026 and IR were studied in the neuroblastoma cell line NGP because of the high PRKDC mRNA expression in this cell line, as determined by Affymetrix microarray analysis." (PMID 26716839, 2015). "Synergistic radiosensitizing effects of NU7026 observed for all tested neuroblastoma cell lines indicate that even the lowest PRKDC mRNA level observed in neuroblastoma cell lines was high enough to induce radiosensitization." (PMID 26716839, 2015). "We therefore evaluated PRKDC mRNA expression levels in human neuroblastoma patients and compared these expression levels with expression levels in non-diseased (normal) tissues." (PMID 26716839, 2015). "We demonstrated that also neuroblastoma express higher levels of PRKDC mRNA compared with normal tissues." (PMID 26716839, 2015). "Radiosensitizing effects of NU7026 were evaluated for neuroblastoma cell lines expressing different PRKDC mRNA levels, including cell lines with the lowest (i.e. SHSY5Y) and highest (i.e. NGP) PRKDC expression." (PMID 26716839, 2015). "We showed that PRKDC levels were enhanced in neuroblastoma patients and correlated with a more advanced tumor stage and poor prognosis, making DNA-PKcs an interesting target for radiosensitization of neuroblastoma tumors." (PMID 26716839, 2015). "As proof of principle, we discover that inhibition of PRKDC, a component of the non-homologous end-joining pathway, sensitizes high-risk neuroblastoma cells to the standard-of-care drug doxorubicin in vitro and in vivo using patient-derived xenograft (PDX) models." (PMID 37957169, 2023). "Results obtained with the small-molecule inhibitor NU7026 were confirmed by PRKDC knockdown, proving that NU7026 radiosensitizes neuroblastoma cells due to DNA-PKcs inhibition." (PMID 26716839, 2015).
thyroid cancer (9 papers, 2016 to 2025). "We have shown that pY397 FAK is localized in the nucleolus in aggressive thyroid cancer cells where it interacts with nucleolar proteins involved in ribosomal biogenesis including NOP56, TOP1, RPL36, and PRKDC." (PMID 40458728, 2025). "NHEJ- (XRCC6, XRCC5, PRKDC) and HR- (SSBP1, SEM1, RPA2, RPA3) related genes are expressed by both normal follicular and thyroid cancer cells." (PMID 38380364, 2024). "NHEJ- (XRCC6, XRCC5, PRKDC) and HR‐ (SSBP1, SEM1, RPA2, RPA3)-related genes were found to be expressed in both normal follicular and thyroid cancer cells." (PMID 38380364, 2024). "These hub genes identified in our study have implications for the response to immune checkpoint inhibitors therapy (PRKDC) and offer potential prognostic markers (CUL1, VAV2), presenting a novel avenue or additional treament for thyroid cancer therapeutics." (PMID 39013964, 2024).
multiple myeloma (8 papers, 2005 to 2024). "Of the MRs, the specific roles of PRKDC and RBL1 and their regulons in DNA damage/repair would be consistent with supporting the maintenance of MDMS8 myeloma cell’s loss of genetic material." (PMID 34922559, 2021). "A predictive model developed by Mohamad and others, based on five genes including CKS1B, CCT2, PRKDC, NONO, and UBE2A, successfully predicted the prognosis of patients with multiple myeloma and has been validated in several independent datasets." (PMID 39046884, 2024).
breast tumors (5 papers, 2014 to 2023). "In addition, some of the DEPs identified in these signaling pathways were also differentially expressed between the male and female breast tumors, such as the ones encoded by CES1, CRYAB, NSF, PRKDC and SERPIND1 genes." (PMID 33656060, 2021).
pulmonary fibrosis (5 papers, 2019 to 2025). Chronic progressive interstitial lung disorder characterized by the replacement of the lung tissue by connective tissue, leading to progressive dyspnea, respiratory failure, or right heart failure. "Lastly, the loss of DNA-PKc was modeled in a humanized model of pulmonary fibrosis in NSG SCID mice genetically deficient in PRKDC (the transcript for DNA-PKcs) and treated with Nu7441." (PMID 31464599, 2019).
asthma (4 papers, 2020 to 2024). "On the other hand, the role of the kinase in inflammation is extremely sensitive to modulation, as a mere 50% reduction in PRKDC by gene heterozygosity protects against asthma in mouse models of the disease." (PMID 38689261, 2024). "While only ~ 1% of PRKDC is necessary for DNA repair, we reported that partial inhibition blocks asthma in mice without causing SCID." (PMID 38689261, 2024). "We previously showed that PRKDC heterozygosity or moderate treatment with the inhibitor NU7441 markedly protected against asthma-like traits in two animal models of the disease, in part, through the inhibition of Th2 cytokines; however, some Th1 cytokines were affected." (PMID 38689261, 2024). "We demonstrated that PRKDC heterozygosity, which reduces the protein level and kinase activity by ~ 50%, blocks asthma through the regulation of gata-3 expression without causing SCID." (PMID 38689261, 2024).
gastric adenocarcinoma (4 papers, 2020 to 2023). "In the Kai Wang's gastric adenocarcinoma cohort, the TMB of PRKDC mut+ samples is significantly higher than in the PRKDC mut− samples only in the MSI‐H subtypes (median nonsynonymous mutations 1467 vs. 553, P < 0.01)." (PMID 32502294, 2020).
microcephaly (4 papers, 2014 to 2025). A congenital or acquired developmental disorder in which the circumference of the head is smaller than normal for the person's age and sex. "Similarly, genes such as PRKDC, ALPL, and KIF23, which are linked to microcephaly (scores ranging from 0.40 to 0.45), are involved in key cellular functions such as DNA repair, motor protein activity, and cytokinesis." (PMID 41033462, 2025). "Recessive biallelic mutations in the PRKDC gene that expresses the catalytic portion of DNA-PK (known as DNA-PKcs) cause IMD26 (Immunodeficiency 26, OMIM 615966), a syndrome that can be accompanied by neurological manifestations, including microcephaly, seizures, and hearing and vision losses." (PMID 32630049, 2020).
skin cutaneous melanoma (4 papers, 2019 to 2023). "Besides, the mutation frequencies of PRKDC in malignancies were dramaticly high, with over 10% of whole tested in uterine corpus endometrial carcinoma (UCEC, 16.57%), skin cutaneous melanoma (SKCM,13.24%), and colon adenocarcinoma (COAD, 10.10%)." (PMID 37854190, 2023).
oral cancer (3 papers, 2013 to 2025). "The present study suggests that MSH3, XRCC5, MRE11A and PRKDC to be the four most important genes that would modify the risk of predisposition to oral cancer and leukoplakia in these eastern Indian populations." (PMID 23437280, 2013). "We performed a case-control association study to identify risk SNPs at major DSB repair (RAD50, MRE11A, NBS1, PRKDC, XRCC5, XRCC6 and LIG4), MMR (MSH6 and MSH3) and key DNA damage response (ATM and ATR) genes in oral cancer and leukoplakia patients from the state of West Bengal of eastern India." (PMID 23437280, 2013).
uterine carcinosarcoma (3 papers, 2020 to 2023). A usually aggressive malignant neoplasm arising from the uterine corpus and less often the cervix. "PRKDC mutation frequency was the highest in UCEC (>18%), and the “amplification” alteration type was the primary type in uterine carcinosarcoma, with an alteration frequency nearby 15%." (PMID 35801800, 2022).
uveal melanoma (3 papers, 2019 to 2023). A melanoma derived from melanocytes of the uveal tract. "We verified these hits effects genetically: we treated the uveal melanoma cell lines depleted of PRKDC or IGF1R with everolimus and, in case of IGF1R, observed a synergistic effect." (PMID 35804957, 2022).
Alzheimer disease (2 papers, 2022 to 2025). A progressive, neurodegenerative disease characterized by loss of function and death of nerve cells in several areas of the brain leading to loss of cognitive function such as memory and language. "Although PRKDC activation normally supports survival under oxidative conditions, chronic activation, as observed in neurodegenerative diseases such as Alzheimer’s disease, can result in maladaptive signaling characterized by persistent inflammation and the accumulation of damaged cells." (PMID 41226761, 2025).
leiomyoma (2 papers, 2013 to 2022). A well-circumscribed benign smooth muscle neoplasm characterized by the presence of spindle cells with cigar-shaped nuclei, interlacing fascicles, and a whorled pattern. "Connecting with the PARP1 hub in leiomyoma from older black women were other genes involved in transcription or DNA repair including PRKDC, catenin (cadherin-associated protein), beta 1subunits, MED4, MED19 and MEDIATOR complex." (PMID 23785396, 2013). "In another study, an array CGH analysis was performed on 23 USMTs (14 STUMPs, 5 LMSs, 3 leiomyomas, and 1 undifferentiated sarcoma), suggesting that the PRKDC and PUM2 genes may have a prognostic role." (PMID 35976464, 2022).
medulloblastoma (2 papers, 2014 to 2023). A malignant, invasive embryonal neoplasm arising from the cerebellum. "In a surveillance of the phosphor-proteomic footprint of medulloblastoma, the DNA-dependent protein kinase PRKDC was predicted to play an important role in group 3 medulloblastomas." (PMID 37568705, 2023). "Consequently, PRKDC inhibitors were investigated for their potential role in therapy, and they were found to elicit radiosensitizing effects in the D458 cell line, which resembles group 3 medulloblastoma with MYC amplification." (PMID 37568705, 2023).
renal carcinoma (2 papers, 2023). A carcinoma arising from the epithelium of the renal parenchyma or the renal pelvis. "Generally, overexpression of PRKDC was observed in most cancers except for renal cancer, in which the level of PRKDC was lower than that in normal tissues." (PMID 37854190, 2023).
schizophrenia (2 papers, 2009 to 2025). A major psychotic disorder characterized by abnormalities in the perception or expression of reality. "Of these genes, 9 genes had protein expression detected in the dorsal lateral prefrontal cortex (dlPFC) and 2 of those (PRKDC and NCALD) were significantly differentially regulated in schizophrenia." (PMID 40181191, 2025).
small cell lung carcinoma (2 papers, 2014 to 2018). Small cell lung cancer (SCLC) is a highly aggressive malignant neoplasm, accounting for 10-15% of lung cancer cases, characterized byrapid growth, and early metastasis. "Moreover, inducible PRKDC knockdown decreased cell viability selectively in high MYC-expressing human small cell lung cancer cell lines." (PMID 25495526, 2014).
Zika virus infection (2 papers, 2022 to 2024). "To determine the role of DNA-PKcs during ZIKV infection, we used CRISPR/Cas9 editing of the PRKDC gene to generate DNA-PKcs-deficient A549 and RPE epithelial cells, referred to as A549PRKDC-/- and RPEPRKDC-/-." (PMID 36311766, 2022). "Similar to what we observed in PRKDC-/- cells, NU7441 pre-treatment increased ZIKV infection in WT, but not in A549PRKDC-/-cells." (PMID 36311766, 2022).
benign ovarian tumor (1 paper, 2024). "The results showed that the mRNA and protein of PRKDC were upregulated in EOC cell lines compared with hEM15A, a kind of benign ovarian tumor cell lineage." (PMID 38732044, 2024).
bone sarcoma (1 paper, 2023). A sarcoma that arises from the bone.
chronic myeloid leukemia (1 paper, 2020). "Similarly, concomitant NU5455 (5 μM) treatment did not alter the response of human chronic myeloid leukemia HAP-1 DNA-PK–null cells to IR, but markedly increased the clonogenic cell-killing effect of 1–4 Gy IR in HAP-1 cells that express 1 copy of PRKDC." (PMID 31581151, 2020).
glomerular disease (1 paper, 2021). "To translate this finding to human glomerular disease, we analyzed whether the C6418T SNP occurs in the human PRKDC gene." (PMID 34423816, 2021).
hepatoblastoma (1 paper, 2023). Hepatoblastoma (HB) is a malignant hepatic tumor and is the most common pediatric liver cancer. "This has led to the identification of a more effective combination therapy in which a PRKDC inhibitor greatly enhances the efficacy of doxorubicin in ABC-Myc mice and human hepatoblastoma xenograft models." (PMID 37414763, 2023).
leukoplakia (1 paper, 2013). A white patch or plaque on a mucous membrane that cannot be characterized clinically or pathologically as any other disease. "Two SNPs (rs12360870 of MRE11A, P-value: 2.37E-07 and rs7003908 of PRKDC, P-value: 7.99E-05) were found to be significantly associated only with leukoplakia." (PMID 23437280, 2013). "Two other loci (rs7003908 of PRKDC and rs12360870 of MRE11A) showed exclusive associations with leukoplakia; one being risk (rs12360870) and the other protective (rs7003908)." (PMID 23437280, 2013).
metastatic melanoma (1 paper, 2020). A melanoma that has spread from its primary site to another anatomic site. "The Allen cohort enrolled 110 patients with metastatic melanoma, and a total of nine patients were identified with PRKDC mutations." (PMID 32502294, 2020).
neurofibroma (1 paper, 2023). An intraneural or extraneural neoplasm arising from nerve tissues and neural sheaths. "In addition to CHEK1, neurofibromas frequently harbor alterations in PRKDC, which may contribute to resistance." (PMID 38136356, 2023).
primary immunodeficiency diseases (1 paper, 2017). "The SGM rabbits we produced in this study can be used for modeling corresponding human primary immunodeficiency diseases: FOXN1 (OMIM# 600838), IL2RG (OMIM# 300400), RAG2 (OMIM# 601457), and PRKDC (OMIM# 600899)." (PMID 28939872, 2017).
prostate tumors (1 paper, 2022). "In advanced prostate tumors, PRKDC is highly activated, promoting progression and metastasis." (PMID 35054819, 2022).
psoriasis (1 paper, 2019). An autoimmune condition characterized by red, well-delineated plaques with silvery scales that are usually on the extensor surfaces and scalp. "The PRKDC may plays a role in the detection and repair of breaks in double-stranded DNA76 and mediates the phosphorylation of c-MYC77 and p5378 suggesting a potentially important role in psoriasis." (PMID 31388062, 2019).
renal dysfunction (1 paper, 2023). "Elevated levels of donor kidney PRKDC are associated with renal dysfunction after transplantation." (PMID 37002788, 2023).